CCDC157 (coiled-coil domain containing 157)
Tractability: No criterion of Open Targets' tractability assessment is met for any kind of drug.
Gene: Protein-coding gene on chromosome 22 (30,356,635 to 30,378,673, forward strand). Ensembl gene ENSG00000187860.
Gene Ontology:
Molecular function: protein binding
Genetic constraint (gnomAD): Loss-of-function variants: 60 observed, 63.83 expected, observed/expected ratio (o/e) 0.94, 90% interval 0.76 to 1.16. The upper end of that interval is the gene's LOEUF score, 1.16, which puts it in group 5 of 6, group 1 being the genes least tolerant of losing a copy. Missense variants: 897 observed, 938.02 expected, observed/expected ratio (o/e) 0.96, 90% interval 0.9 to 1.01. Synonymous variants: 359 observed, 394.33 expected, observed/expected ratio (o/e) 0.91, 90% interval 0.83 to 0.99.
Homologues: Orthologues: chimpanzee CCDC157 (96% identical), macaque CCDC157 (94% identical), dog CCDC157 (75% identical), mouse Ccdc157 (73% identical), rabbit CCDC157 (72% identical), rat Ccdc157 (72% identical), guinea pig CCDC157 (70% identical), zebrafish ccdc157 (31% identical), Caenorhabditis elegans citk-1 (14% identical), Caenorhabditis elegans citk-2 (14% identical), Drosophila melanogaster SMC3 (10% identical), Caenorhabditis elegans smc-3 (9% identical). Paralogues in human: SMC1B (14% identical), SMC1A (13% identical), SMC2 (13% identical), SMC3 (13% identical), SMC4 (13% identical), CKAP4 (9% identical), CCDC122 (5% identical).
Diseases named in the same sentence as CCDC157 in open-access papers:
CCDC157 is named in the same sentence as 12 diseases in open-access papers, as found by Europe PMC text mining. Sharing a sentence is not in itself a finding about the gene and the disease. The quoted sentences say what the papers report.
Azoospermia (2 papers, 2019 to 2022). Absence of any measurable level of sperm,whereby spermatozoa cannot be observed even after centrifugation of the semen pellet. "Human CCDC157, with unknown function, was identified to be downregulated in men with idiopathic non-obstructive azoospermia (NOA)." (PMID 30741974, 2019).
male infertile (2 papers, 2019 to 2024). "In conclusion, we have identified a male infertile‐associated gene, CCDC157, as indispensable for spermiogenesis." (PMID 38509755, 2024). "In searching for genetic causes of male infertility, we also focused on a consanguineous Pakistani pedigree linked to a CCDC157 mutation." (PMID 38509755, 2024). "To investigate the mechanism of the mutation of CCDC157 involved in male infertility, we employed CRISPR/Cas9 to generate Ccdc157 mutants in mice." (PMID 38509755, 2024). "Thus, we considered that, for these cases, CCDC157 was also a candidate gene responsible for OAT, causing male infertility in this family." (PMID 38509755, 2024). "Our study may inform the potential roles of CCDC157 in human spermatogenesis and may provide a new target for the treatment of human male infertility." (PMID 30741974, 2019).
infertile (1 paper, 2024). "However further research is needed to confirm the therapeutic effect and mechanism of the Huangjin Zanyu on infertility caused by CCDC157 deficiency or from other causes." (PMID 38509755, 2024).
oligospermia (1 paper, 2024). Decreased number of spermatozoa in the semen. "Using the Huangjin Zanyu Chinese medicine as a treatment, the oligospermia due to heterozygous mutation of CCDC157 in mice and humans was alleviated to a significant measure." (PMID 38509755, 2024).
Sepsis (1 paper, 2025). Sepsis is defined as life-threatening organ dysfunction caused by a dysregulated host response to infection. "Rare variants in LTBP4 are significantly associated with the most severe pediatric sepsis phenotype (PedSep-D), while variants in PLA2G4E and CCDC157 show associations with this phenotype in suggestive significance." (PMID 41076474, 2025).
tumor (1 paper, 2024). "Among the downregulated DEGs, four genes (LAMA1, ASPRV1, IL1B, PRR4) displayed reduced expression, while two genes (CCDC157, RP1) showcased elevated expression in tumor compared to normal tissue, respectively." (PMID 39062832, 2024).
CCDC157 also shares sentences with these, for which no sentence is quoted: cancer (1 paper); endometrial cancer (1); Ewing sarcoma (1); oligoasthenoteratozoospermia (1); ovarian carcinoma (1); prostate carcinoma (1).